METTL3 (methyltransferase 3, N6-adenosine-methyltransferase complex catalytic subunit)
Diseases named in the same sentence as METTL3 in open-access papers (continued):
Sharing a sentence is not in itself a finding about the gene and the disease.
seminoma (12 papers, 2020 to 2025). A radiosensitive malignant germ cell tumor found in the testis (especially undescended), and extragonadal sites (anterior mediastinum and pineal gland). "They discovered a marked upregulation of METTL3 in a cisplatin‐resistant TCam‐2 cell line derived from seminoma, which led to an increase in autophagy and a decrease in sensitivity to cisplatin." (PMID 38332508, 2024). "This highlights the potential of METTL3 as a therapeutic target to overcome cisplatin resistance in seminoma." (PMID 38332508, 2024). "Low expression of METTL3 as a prognostic biomarker is associated with lower OS and DFS rates in GCT and exerts therapeutic effects in seminomas." (PMID 38332508, 2024). "In summary, METTL3 overexpression is deleterious to asthenozoospermia and seminoma chemotherapy, but is therapeutic for GSC." (PMID 38332508, 2024). "To summarize, METTL3 expression is significantly upregulated in GCT and downregulated in seminomas, suggesting a distinct role for METTL3 in male reproductive tumours." (PMID 38332508, 2024). "In the seminoma of H. sapiens, upregulation of METTL3 can increase the m6A level of ATG5 transcript, which increases the expression of ATG548." (PMID 37210465, 2023). "In seminoma, METTL3 was highly expressed in resistant seminoma cell and inhibition of METTL3 enhanced the response to cisplatin treatment." (PMID 36810281, 2023). "This is in line with a recent study by Wei and collaborators, who demonstrated that METTL3 promotes resistance by introducing m6A in TFAP2C in the seminoma-like cell line TCam-2, both in vitro and in vivo." (PMID 34446080, 2021). "This indicates that METTL3 contributes to cisplatin resistance in the seminoma phenotype, and supports an oncogenic role for this player." (PMID 34446080, 2021). "In our assays in the present study, the biological effect of METTL3 overexpression on seminoma cells was attenuated or reversed by inhibition of IGF2BP1, suggesting a close relation and synergism of the ‘writer’ and ‘reader’ in m6A modification." (PMID 32857912, 2020). "Conversely, in seminomas, high levels of METTL3 play an oncogenic role by enhancing cisplatin resistance during treatment, indicating that lower levels of METTL3 may be beneficial in seminoma therapy." (PMID 38332508, 2024). "In seminoma 54, METTL3 could increase autophagy by modulating ATG5, thus promoting cisplatin resistance." (PMID 36632456, 2023). "Therefore, METTL3 was a potential therapeutic target to reverse cisplatin resistance in seminoma." (PMID 36632456, 2023). "TFAP2c, the transcription factor AP-2 family member, was methylated by METTL3 and recognized by IGF2BP1, which enhances the mRNA stability of TFAP2c, thereby making seminoma resistant to cisplatin." (PMID 40180937, 2025). "In seminoma, m6A methylation of TFAP2C mRNA initiated by METTL3, in conjunction with the other mechanisms, gives the tumour cells more time to develop resistance to CDDP treatment." (PMID 32857912, 2020). "To partially compensate for this deficiency, we leveraged The Cancer Genome Atlas (TCGA) database and studied the mRNA levels of METTL3 and TFAP2C in seminoma and non‐seminoma samples." (PMID 32857912, 2020). "Collectively, we showed the interactions of the METTL3/IGF2BP1/TFAP2C signalling pathway and unveiled its contributions to in vivo CDDP resistance in seminoma." (PMID 32857912, 2020). "Owing to the difficulty in obtaining samples from CDDP‐resistant seminoma cases, we were not able to detect the expressions of METTL3 and TFAP2C in clinical chemo‐resistant samples." (PMID 32857912, 2020). "For example, methyltransferase‐like 3 (METTL3) could stabilise the transcription factor AP‐2 gamma (TFAP2C) mRNA in an insulin‐like growth factor 2 mRNA binding protein 1 (IGF2BP1)‐dependent mode and further enhance cisplatin resistance in seminoma." (PMID 35696608, 2022).
seminoma (continued). "Two molecules, methyltransferase‐like protein 3 (METTL3) and insulin‐like growth factor 2 mRNA‐binding protein 1 (IGF2BP1), were found to play crucial roles in potentiating resistance to CDDP through m6A methylation of transcription factor‐activating enhancer‐binding protein 2C (TFAP2C) in seminoma." (PMID 32857912, 2020).
acute kidney injury (11 papers, 2023 to 2025). Sudden and sustained deterioration of the kidney function characterized by decreased glomerular filtration rate, increased serum creatinine or oliguria. "Moreover, METTL3 has been implicated in different acute kidney injury (AKI) models as well as in human biopsies and cultured tubular epithelial cells (TECs), and the METTL3-targeted inhibitor Cpd-564 has demonstrated efficacy in ameliorating renal dysfunction and suppressing inflammation." (PMID 41142801, 2025). "In addition, cisplatin-induced acute kidney injury in mice led to increased m6A levels and alterations in the expression of methyltransferase complexes, including METTL3, METTL14, FTO, and ALKBH541." (PMID 38297163, 2024). "Another study found increased expression of METTL3 in renal TECs in acute kidney injury." (PMID 37865763, 2023). "Our previous study has discovered that METTL3 is consistently induced in mouse models of acute kidney injury (AKI) as well as in human biopsies of AKI, demonstrating its significant association with renal inflammation and injury." (PMID 40100069, 2025). "Studies in acute kidney injury (AKI) have verified the inhibitory effect of BBR hydrochloride on METTL3 expression and demonstrated that BBR ameliorated folic acid-induced AKI and H2O2-induced pyroptosis in TCMK-1 cells by inhibiting METTL3." (PMID 40829428, 2025). "Inhibition of METTL3 obviously alleviates renal injury and inflammation through IGF2BP2-dependent mechanisms, which suggests that targeting METTL3 may be a promising therapeutic approach for acute kidney injury (AKI)." (PMID 37006311, 2023).
Insulin resistance (11 papers, 2020 to 2025). Increased resistance towards insulin, that is, diminished effectiveness of insulin in reducing blood glucose levels. "In the context of diabetes mellitus, inhibiting METTL3 activity has been shown to diminish the m6A modification levels of genes associated with insulin resistance, consequently enhancing insulin sensitivity." (PMID 40066222, 2025). "The m6A methylation levels and METTL3 expression were raised in the livers of obese mice, and hepatocyte-specific knockout of METTL3 improved lipid metabolic disorders and insulin resistance." (PMID 35057432, 2022). "To determine whether BAT METTL3 regulates systemic glucose homeostasis and insulin resistance, we performed glucose tolerance tests and insulin tolerance tests on mice fed with HFD for 8 weeks (16 weeks old)." (PMID 32245957, 2020). "Adeno-associated virus (AAV)-mediated liver-specific overexpression of Mettl3 aggravated HFD-induced liver metabolic disorders and insulin resistance." (PMID 33160098, 2020). "Overexpression of Mettl3 aggravated HFD-induced liver metabolic disorders and insulin resistance." (PMID 33160098, 2020). "Additionally, other m6A regulators such as METTL3 and METTL14 have been reported to participate in the regulation of insulin resistance." (PMID 32733807, 2020).
lung injury (11 papers, 2020 to 2025). "A previous report showed that m6A modification levels in total RNA were decreased in the hippocampus after traumatic brain injury, which could be due to the downregulation of METTL3." (PMID 33796004, 2021). "SNHG4 inhibited METTL3‐mediated m6A level of STAT2 mRNA, which resulted in the alleviated LPS‐induced inflammatory lung injury." (PMID 36565037, 2023). "In the mouse model of acute lung injury (ALI) lacking METTL3, there was a reduction in both lung damage and the levels of proinflammatory cytokines compared to the ALI mouse model with normal METTL3 expression." (PMID 39010105, 2024).
pancreatic ductal adenocarcinoma (11 papers, 2019 to 2026). An infiltrating adenocarcinoma that arises from the epithelial cells of the pancreas. "CSC increases transcription factor NFIC in the METTL3 promoter region and elevates METTL3 transcription in pancreatic ductal adenocarcinoma cells." (PMID 37996892, 2023). "For example, during pancreatic ductal adenocarcinoma (PDAC) tumorigenesis cigarette smoke condensate (CSC) promotes the maturation of miR-25-3p through mediating METTL3." (PMID 36226036, 2022). "This suggests that METTL3/14 could potentially regulate the immune microenvironment in pancreatic ductal adenocarcinoma." (PMID 38187373, 2023). "In pancreatic ductal adenocarcinoma, METTL3 accelerates the maturation of the miR-25-3p precursor." (PMID 37996892, 2023). "Another study reported that the upregulation of METTL3 caused an increase in miR-25-3p and that miR-25-3p could promote the expression of its target protein PHLPP2 to promote pancreatic ductal adenocarcinoma occurrence." (PMID 31757221, 2019). "Ultimately, the study revealed that the METTL3-miR-25-3p-PHLPP2-AKT regulatory axis might influence the transformation of pancreatic ductal adenocarcinoma induced by cigarette smoking." (PMID 31757221, 2019). "This study analyzed eight m6A regulators (METTL3, METTL14, WTAP, FTO, ALKBH5, and YTHDF1-3) in pancreatic ductal adenocarcinoma (PDAC) and found that only RNA m6A demethylase ALKBH5 serves as an independent favorable prognostic marker for this tumor." (PMID 34733841, 2021).
type 2 diabetes (11 papers, 2020 to 2025). "Other studies have described a decrease in m6A methylation in the pancreatic islets of patients with type 2 diabetes, associated with a decreased expression of the methyltransferases METTL3 and METTL14." (PMID 35053407, 2022). "METTL3 was up-regulated in patients with type 2 diabetes and mice with high-fat diet, and inhibited insulin sensitivity and promoted fatty acid metabolism." (PMID 34503454, 2021). "Therefore, the METTL14/METTL3/G6pc mRNA m6A pathway may serve as new therapeutic targets for type 2 diabetes treatment." (PMID 40278833, 2025). "In a recent study, demethylases FTO have been demonstrated to positively correlate with methyltransferases methyltransferase complex (METTL3, METTL14, and WTAP) in patients with type 2 diabetes." (PMID 32583611, 2020). "We postulated that obesogenic factors might upregulate hepatic METTL14 and METTL3 to activate the G6pc mRNA m6A/G6pc synthesis/HGP pathway, thereby exacerbating type 2 diabetes progression." (PMID 40278833, 2025).
fibrosis (10 papers, 2022 to 2025). the formation of excess fibrous connective tissue in an organ or tissue in a reparative or reactive process. "METTL3 depletion reduced the body weight loss and increased the pulmonary coefficient secondary to fibrosis." (PMID 37072646, 2023). "The current study revealed that METTL3 expression was up‐regulated in irradiated hearts, thereby intensifying cardiac fibrosis." (PMID 40471098, 2025). "Next, we investigated the effects of a METTL3-specific inhibitor in HK-2 cells challenged with TGF-β in an in vitro fibrosis model and a 14-day UUO in vivo mouse model." (PMID 38297163, 2024). "The results of western blot assay and dot-blots assay demonstrated that, compared to that in LR-MSCs from the mouse in sham group, both the levels of METTL3 expression and m6A modification were increased in LR-MSCs from the bleomycin-induced fibrosis model." (PMID 38017523, 2023). "Smad2/3 are key regulators of the fibrogenesis process in cardiac fibroblasts, whereas silencing METTL3 reduced the upregulation of Smad2/3 induced by TGF-β1, suggesting that METTL3 regulated cardiac fibrosis at least partially through Smad-mediated pathway." (PMID 35224032, 2022).
lymph node metastasis (10 papers, 2020 to 2025). "METTL3 was shown to be upregulated in CC cells and linked to lymph node metastasis and unfavorable outcomes." (PMID 36050747, 2022). "The results indicated that lower expression levels of METTL3 and METTL14 were associated with increased lymph node metastasis (N1‐N2), enhanced distal metastasis (M1), and poorer patient survival." (PMID 40785027, 2025). "The analysis results suggested that low METTL3 expression was positively correlated with advanced T stage, lymph node metastasis and AJCC-defined stage of extrathyroidal extension." (PMID 38993572, 2024). "The METTL3 high expression group was associated with advanced TNM and higher degrees of distant metastasis and lymph node metastasis (p < 0.05)." (PMID 35742899, 2022). "In total, we examined METTL3 expression in 455 paraffin-embedded blocks (paratumor, n = 146; primary tumor, n = 196; lymph node metastasis, n = 92; distant metastasis, n = 21)." (PMID 32175271, 2020). "Moreover, chi-square analysis further suggested that low METTL3 expression was positively correlated with advanced T stage, lymph node metastasis and the American Joint Committee on Cancer (AJCC)-defined stage of extrathyroidal extension." (PMID 38993572, 2024). "METTL3, YTHDC2, YTHDF1, and YTHDF2 had a remarkably high expression in PCa and CRPC with lymph node metastasis." (PMID 33403026, 2021). "METTL3 expression significantly correlated with AJCC staging (the eighth edition, P = 0.0056), lymph node metastasis (P = 0.0251), and vascular invasion (P = 0.0346), but did not correlate with gender, age, differentiation, and tumor invasion." (PMID 33037176, 2020). "The expression of METTL3, METTL14, WTAP, YTHDC2, YTHDF1, and YTHDF2 was remarkably higher in CRPC with lymph node metastasis than in CRPC with bone metastasis, whereas ALKBH5, FTO, and YTHDF3 were substantially decreased in CRPC with lymph node metastasis." (PMID 33403026, 2021).
autoimmune disease (9 papers, 2020 to 2025). A disorder resulting from loss of function or tissue destruction of an organ or multiple organs, arising from humoral or cellular immune responses of the individual to their own tissue constituents. "Together, these data suggest that METTL3 controls pathogenic Th17 responses, and targeting METTL3 may contribute to human autoimmune disease therapy." (PMID 39416774, 2024). "Although we have previously shown that METTL3 polymorphisms confer risk for the susceptibility of GD and mRNA m6A modification is known to regulate immune cell differentiation and immune response and is involved in the development of some autoimmune diseases." (PMID 34616359, 2021). "For instance, manipulating METTL3 activity might offer new avenues for treating chronic inflammatory diseases, cancer, and autoimmune disorders by modulating macrophage polarization and function." (PMID 39416774, 2024). "Furthermore, studies have found that autoantibodies such as ANA (antinuclear antibodies), IgG-anti-MX1, and IgG-anti-METTL3 are elevated in patients with autoimmune diseases related to the COVID-19 vaccine." (PMID 39021569, 2024). "However, homozygous Foxp3-Mettl14f/f cKO mice developed a severe autoimmune disease and died within eight to twelve weeks, similar to the results for Mettl3-Treg cKO mice." (PMID 36341394, 2022). "For instance, investigating how METTL3 regulates the differentiation and function of DCs under different pathological conditions may unveil novel mechanisms of immune modulation that can be targeted in autoimmune diseases or cancer." (PMID 39416774, 2024).
cyst (9 papers, 2021 to 2026). A sac-like closed membranous structure that may be empty or contain fluid or amorphous material. "Surprisingly, we noted that PC2 derepression was associated with reduced 3D cyst growth, restored MitoTracker signal, and downregulation of pCreb1, Yap1, Mettl3, and c-Myc expression in Pkd1RC/-; Pkd2∆17/∆17 cells compared to Pkd1RC/- cells." (PMID 35965273, 2022). "Therapeutically, transgenic METTL3 deletion attenuates cyst expansion in murine models, while dietary methionine restriction demonstrates clinical potential by disrupting these metabolic-epigenetic interactions." (PMID 40895041, 2025). "In a mouse cystic disease model, METTL3 deletion suppressed cyst formation, and the methionine-METLL3-c-Myc/Camp pathway was involved in the pathogenesis of cystic kidney disease." (PMID 38297163, 2024). "Elevated levels of methionine and s-adenosylmethionine (SAM) in the ADPKD model induced METTL3 expression and exacerbated isolated cyst growth, whereas dietary restriction of methionine attenuated ADPKD in mice." (PMID 38066436, 2023). "METTL3 promotes cyst proliferation and new protein synthesis by enhancing c-Myc and Avpr2 mRNA m6A modification and translational activation of the cyst-promoting c-Myc and cAMP pathway via c-Myc and cAMP signaling." (PMID 38066436, 2023). "Previous research in Drosophila spermatogenesis suggests that somatic cyst cell specific knockdown of Mettl3 leads to misregulation of an essential protein profilin (chic), which disrupts the somatic permeability barrier." (PMID 35071998, 2022). "We used the Gal4-UAS system to ubiquitously knockdown Mettl3 in both somatic cyst cells and germline cells." (PMID 35071998, 2022). "Furthermore, in autosomal dominant polycystic kidney disease, a hyperactive METTL3-m6A axis enhances the translation of pro-proliferative mRNAs like c-Myc, accelerating cyst growth." (PMID 41607591, 2026). "Kidney-tubule-specific Mettl3 overexpression induced the occurrence and enlargement of tubular cysts, and conversely, Mettl3 deletion attenuated cyst growth in three different orthologous ADPKD transgenic mouse models, irrespective of the type of PKD1 mutation or dynamics of cyst growth." (PMID 35865176, 2022). "As for therapy, a vegan-based diet could also be used to ameliorate cyst formation, as methionine is found in meat and fish; alternatively, METTL3 inhibitors may also be targetable for ADPKD but warrants further investigation." (PMID 34901057, 2021). "Preclinical interventions targeting METTL3 or ALKBH5 have shown efficacy in attenuating renal fibrosis, inflammation, and cyst expansion." (PMID 41607591, 2026). "Moreover, dietary methionine and S-adenosylme thionine, which could induce Mettl3 expression, aggravated cyst growth ex vivo; in contrast, dietary methionine restriction attenuated mouse ADPKD, indicating a potential dietary therapy to slow down disease progression." (PMID 35865176, 2022). "Furthermore, gradually declining METTL3 expression is related to an increased r-AFS stage, larger cyst size and DIE." (PMID 37353804, 2023).
diffuse large B-cell lymphoma (9 papers, 2021 to 2025). "Studies have shown that METTL3 inhibits the complement pathway by mediating C1qA methylation and enhances resistance to Rituximab, thereby facilitating the progression of diffuse large B-cell lymphoma (DLBCL)." (PMID 38902779, 2024). "Cheng Y and colleagues found that the m6A methylation level was upregulated in diffuse large B-cell lymphoma (DLBCL) and that METTL3 promoted disease progression." (PMID 35734168, 2022). "Another study showed that in diffuse large B-cell lymphoma (DLBCL), METTL3 expression and m6A level were increased in both tissue and cell lines." (PMID 37325513, 2023). "In addition, elevation of METTL3 in diffuse large B-cell lymphoma (DLBCL) promoted the expression of pigment epithelium-derived factor (PEDF) transcripts, thereby activating the Wnt pathway to accelerate cell proliferation." (PMID 33879256, 2021). "In diffuse large B-cell lymphoma (DLBCL), m6A level and METTL3 expression are increased both in tissues and cell lines." (PMID 34103054, 2021).